APLN (apelin)
Diseases named in the same sentence as APLN in open-access papers (continued):
Sharing a sentence is not in itself a finding about the gene and the disease.
tumor (continued). "Patients with high tumor apelin expression had a shorter overall survival period than those with low apelin expression." (PMID 29875677, 2018). "In NSCLC the level of apelin mRNA and apelin-36 peptide were significantly higher in the patient's tumor samples compared to normal tissue." (PMID 29875677, 2018). "In contrast to other putative bvz biomarkers, which are not directly linked to the tumour vascularisation or are related to various functions in tumour cells, APLN is produced and secreted by TECs directly." (PMID 28487489, 2017). "Tumor growth was obviously inhibited after blocking apelin/APJ signaling with exogenous F13A in a HCC subcutaneous mouse tumor model, compared to the control group." (PMID 28484393, 2017). "In keeping with this, a recent study proposed apelin as a marker for monitoring tumour vessel normalization and response to anti-angiogenic therapy." (PMID 29053791, 2017). "Here, we demonstrate that apelin is released by human, mouse and tumour-derived endothelial cells in vitro, although this secretion was not overtly affected by the acidification of the milieu." (PMID 29053791, 2017). "Similar to VEGF, APLN has been shown to act as vascular chemo-attractant and its expression is induced in sprouting vessels under pathological conditions e.g. in tumours." (PMID 28487489, 2017). "Recently, Zhang and co-workers described a decrease in APLN levels following bvz treatment in mice, resulting in stabilisation of the tumour vasculature." (PMID 28487489, 2017). "The contradiction of this slight elevation compared to the microarray data, in which APLN was equally expressed in whole tissue samples of tumour and bulk, can be explained by the fact that the qRT-PCR approach is more sensitive." (PMID 28487489, 2017). "Apelin is an angiogenic factor secreted by tumor cells in order to promote the formation of new vessels necessary for tumor growth." (PMID 27484806, 2016). "Using Apelin as a marker to monitor tumor vessel normalization window during anti-angiogenic therapy was reported." (PMID 27733135, 2016). "Our data suggest that tumor Apelin is a protein marker to evaluate the clinical features and to predict post-operative prognosis in GC patients." (PMID 27733135, 2016). "Our data suggest that tumor Apelin can be used as a marker to evaluate clinical characteristics and predict prognosis in GC patients." (PMID 27733135, 2016). "Previous experimental and clinical studies suggest that Apelin is a mitogenic factor for the endothelial cells and stimulates tumor angiogenesis." (PMID 27733135, 2016). "In this study, we enrolled GC patients to further investigate the role of tumor and serum Apelin in the clinical features, in particular, disease characteristics and prognosis in GC patients." (PMID 27733135, 2016). "Our data showed that tumor Apelin expression status, instead of serum Apelin level, was closely associated with more advance clinical features including tumor differentiation, lymph node and distant metastases." (PMID 27733135, 2016). "We next investigated the relationship between tumor Apelin expression status and clinical characteristics of GC patients." (PMID 27733135, 2016). "A previous study suggest that tumor patients had higher Apelin levels compared with healthy controls, and Apelin is closely related to the disease stages and progression independently of other potential confounders." (PMID 27733135, 2016). "We further analyzed the relation of tumor Apelin expression status with the survival of GC patients in this study." (PMID 27733135, 2016). "The tumor and serum Apelin levels were determined by immunohistochemistry and ELISA methods, respectively." (PMID 27733135, 2016). "Apelin level in tumor tissue was somewhat higher than in the normal mucosa (22.9 ± 18.5 ng/g of tissue versus 16.9 ± 8.9 ng/g of tissue, P = 0.036)." (PMID 25049439, 2014).
tumor (continued). "It has also been demonstrated that apelin can induce the maturation of tumor blood capillaries and, moreover, that the apelin-APJ system is able to increase the vascularization and growth of different murine tumors." (PMID 24962866, 2014). "There was a weak positive correlation between serum apelin concentrations and their levels in tumor tissue (r = 0.30, P = 0.029)." (PMID 25049439, 2014). "In conclusion, our study identifies apelin as a novel tumor lymphangiogenic factor that enhances LN metastasis." (PMID 24962866, 2014). "It has been reported in experimental and clinical studies that apelin is a mitogenic factor for the endothelial cells and stimulates tumor angiogenesis." (PMID 25049439, 2014). "In turn, apelin 14 was conjugated to rhodamine-encapsulating liposomes and administered to tumor-bearing mice." (PMID 23799018, 2013). "It has been reported that apelin has a regulatory effect on cardiovascular system, appetite, drinking behaviors, neoangiogenesis, lymphangiogenesis, fibrogenesis, and tumor growth." (PMID 23476106, 2013). "Adipokines such as chemerin, resistin, leptin, and apelin contribute to tumour progression." (PMID 42135288, 2026). "Furthermore, ST feature plots and results of deconvolution analysis showed that APLN+ endothelial cells surrounded the pro-metastatic region of tumor cells, and the expression levels of key marker genes were highly expressed." (PMID 39741182, 2025). "The mechanism underlying these processes is of dysregulation of PRAT’s secretion of adipokines and pro-inflammatory cytokines, such as leptin, adiponectin, chemerin, apelin, omentin-1, vistatin, nesfatin-1, and other pro-inflammatory cytokines, modulated by tumor cells." (PMID 40227577, 2025). "Furthermore, stromal cells in the tumor microenvironment, including MMP3+IL24+ fibroblasts, APLN+ endothelial cells, and CXCL12+ pericytes, were implicated in ESCC metastasis through angiogenesis, collagen production, and inflammatory responses." (PMID 39741182, 2025). "In addition, MC-38 cells produce more apelin compared to CT-26 cells, suggesting the potential involvement of one or more of these differences in the lower anti-tumor efficacy of APLN-DM expression in MC-38 cells compared to CT-26 cells." (PMID 39962271, 2025). "A recent study has demonstrated that inhibition of APLN could profoundly suppress angiogenesis-dependent tumor growth, suggesting the pivotal role of APLN in remodeling the TME and facilitating angiogenesis." (PMID 39741182, 2025). "It was also reported that inhibition of apelin reduces angiogenesis and, therefore, tumor growth." (PMID 39040042, 2024). "Moreover, in vitro and in vivo experiments using colon and prostate cancer cell lines have reported that high apelin expression alters the vascular structure and immune environment, resulting in a reduction in tumor size." (PMID 38238841, 2024). "Crucially, both apelin peptide and the receptor are upregulated in GBM patient samples, and, in an orthotopic mouse model of GBM, apelin was required for tumour vascularisation, where apelin depletion significantly reduced tumour size and increased survival of tumour-bearing mice." (PMID 38803685, 2024). "Additionally, tumour cells with high levels of Apelin/APJ expression exhibit an increased tendency for metastasis." (PMID 39434201, 2024). "This suggests that Capillaries have higher stemness, aligning with previous conclusions and indicating that the apelin/APJ system may promote tumour metastasis by facilitating the formation of intratumoural microcapillaries." (PMID 39434201, 2024). "Moreover, angiogenesis induced by the Apelin/APJ axis is another critical factor contributing to tumour progression." (PMID 39434201, 2024). "Moreover, analysis of patients' clinical data revealed that the HR group were more susceptible to portal vein invasion, suggesting a potential role of apelin/APJ in promoting tumour metastasis through the formation of PVTT." (PMID 39434201, 2024).
tumor (continued). "However, under pathological conditions such as tumour proliferation and myocardial infarction, there is an increase in the expression of Apelin/APJ in ECs." (PMID 39434201, 2024). "APLN has previously been shown to stimulate tumor metastasis." (PMID 36632453, 2023). "Many studies reported that apelin-13 can stimulate tumor proliferation and metastasis." (PMID 36614283, 2023). "Several reports indicate that apelin is often over-expressed in tumors, and therefore it has been suggested that the apelin–apelin receptor (APJ) system may induce tumor progression." (PMID 36776217, 2023). "During normal blood vessel development, APLN can act as an active substance to stimulate the proliferation and migration of endothelial cells; therefore, APLN has also been confirmed as a potentially important factor in promoting tumor angiogenesis." (PMID 36614283, 2023). "In contrast, our previous research revealed high expression of the apelin–APJ system in tumor blood vessels, suggesting its involvement in the regulation of tumor vessel formation and normalization, resulting in the suppression of tumor growth by promoting the infiltration of T cells." (PMID 36776217, 2023). "In addition, APLN and its receptors are involved in signaling pathways related to migration and invasion, leading to tumor growth and metastasis." (PMID 36614283, 2023). "Discrepancies in tumor growth affected by apelin may due to the expression of its receptor, APJ, in the tumor microenvironment." (PMID 36776217, 2023). "Tumor growth by LLC or MC38 cells was enhanced significantly in apelin-knockout (KO) mice." (PMID 36776217, 2023). "Evaluation of association between apelin/APJ and clinicopathological features of PDAC patients did not reveal any significant correlation between apelin or its receptor expression and gender, age or tumor stage." (PMID 36142542, 2022). "Considering the role of apelin in tumor angiogenesis and metastasis, we hypothesized that apelin may also contribute to the metastatic transformation in PPGLs." (PMID 35574028, 2022). "Apelin may contribute to tumor angiogenesis and metastasis by mediating several pathways related to angiogenesis, cell migration, and cell invasion." (PMID 35574028, 2022). "This hypothesis is supported by a significant body of research showing increased apelin concentration and overexpression of the APJ receptor for which apelin is a ligand in tumor tissue." (PMID 36230579, 2022). "Additionally, apelin favors tumor progression by promoting proliferation, cell migration, invasion, angiogenesis, and metastasis." (PMID 36291097, 2022). "The risk of metastasis was significantly higher if negative apelin expression was detected in the tumor tissue." (PMID 35574028, 2022). "Interestingly, apelin expression levels in serum, as well as in tumors, positively correlated with tumor progression and decreased overall survival." (PMID 36142542, 2022). "Hence, we aimed to retrospectively collect pathologically identified PPGL tumor tissues from our center and investigate the expression of apelin and SUCLG2 along with previously studied ERBB-2, CNTN4, CHGB, and SDHB in metastatic and non-metastatic PPGLs." (PMID 35574028, 2022). "Notably, we found more apelin protein content in C26 than 4T1, supporting the increased plasma apelin as tumor-derived in cachectic conditions." (PMID 35406586, 2022). "In addition to obesity, the high tumor apelin expressions were related to a blunted response to N-acetylcysteine in their breast cancer cohort." (PMID 35701840, 2022). "In a subcutaneous tumor model, APLN overexpression reduced the leakiness of the tumor vasculature." (PMID 34359800, 2021). "In tumors from [Pyr1]Apelin-13-infused mice (designated WT + [Pyr1]Apelin-13), total vessel length was shorter than in tumors from un-infused mice both at the edge and center of the tumor." (PMID 34234274, 2021). "Therefore, we infused [Pyr1]Apelin-13 into Apelin-KO mice that had been inoculated with MC38 tumor cells." (PMID 34234274, 2021).
tumor (continued). "In MC38 tumors, only endothelial cells (ECs) strongly express APJ, a cognate receptor for Apelin, indicating that EC-derived Apelin might regulate tumor formation in an autocrine manner." (PMID 34234274, 2021). "High expression of apelin significantly correlated with high tumor stage, distant metastasis, vascular invasion and may have the potential to indicate poor prognosis." (PMID 33912466, 2021). "We found that CCL8 was more highly expressed in tumor ECs from WT than Apelin-KO mice." (PMID 34234274, 2021). "Furthermore, a subsequent APLN inhibition trial on KIRC PDX mice supported its potential function in KIRC tumor progression." (PMID 35079698, 2021). "In addition, we discuss how manipulation of APLN/APLNR signaling in GBM leads to the normalization of tumor vessels and thereby supports chemotherapy, reduces edema, and improves anti-tumorigenic immune reactions." (PMID 34359800, 2021). "Subsequent experiments also supported the potential role of APLN in KIRC tumor progression." (PMID 35079698, 2021). "Also, tumor progression induced by APLN's overexpression in UM-RC-2 seemed to depend on the stomal involvement." (PMID 35079698, 2021). "Along with the maturation of tumor vasculature, infiltration of T cells might also be altered by Apelin." (PMID 34234274, 2021). "However, the distribution of CD8+ and CD4+ T cells detected by immunofluorescence staining in different regions of the tumor revealed that higher numbers of CD8+ T cells accumulated in the center of tumors from WT mice than Apelin-KO mice." (PMID 34234274, 2021). "In addition, the host–microbiota crosstalk of EC endometrium also included many biological processes, mainly functions related to tumor migration and the Apelin signaling pathway." (PMID 34631710, 2021). "Therefore, we analysed CCL8 receptor expression in the tumor microenvironment and consider how the Apelin/CCL8 axis is involved in tumor immunity." (PMID 34234274, 2021). "In our MC38 and LLC tumor models, Apelin also inhibited tumor growth." (PMID 34234274, 2021). "On the other hand, several lines of evidence indicate that Apelin is often over-expressed in tumors, and it has been suggested that this factor may induce tumor growth because its expression correlates with tumor malignancy." (PMID 34234274, 2021). "The apelin expression correlated with poor overall survival (OS) and apelin could stimulate tumor growth and microvessel densities in vivo in NSCLC." (PMID 33912466, 2021). "We hypothesized that tumour growth might be enhanced by a stimulatory effect of apelin on lymph vessel formation." (PMID 33707612, 2021). "Thus, Apelin showed tumor growth inhibitory activity in mice, especially in these MC38 and LLC subcutaneously inoculated tumor models." (PMID 34234274, 2021). "Interestingly, only BMI [Odds ratio (OR) of 0.86, 95% confidence interval (CI) 0.74–0.99] and tumor apelin expression (OR of 0.90, 95% CI 0.83–0.97) were significantly associated with pCR in the multivariate analysis." (PMID 33972642, 2021). "Consistent with this, treating WT mice with [Pyr1]Apelin-13 inhibited tumor growth." (PMID 34234274, 2021). "In addition to the strong expression in tumor vessels, APLN was also detected in GBM pseudopalisades, which represent another hallmark of this entity and are formed by radially oriented neoplastic cells surrounding band like necroses." (PMID 34359800, 2021). "In addition, Apelin deficiency attenuated the vascular luminal space and induced merely cord-like structures of CD31-positive ECs in the central tumor area, different from tumors in WT mice." (PMID 34234274, 2021). "This hypothesis was further confirmed by the significant increase of angiopoietin 1 and Pecam1 mRNA expression and by histological analysis of Pecam1 staining in apelin‐infused tumours." (PMID 32681609, 2020). "In tumors, increased levels of Apelin promote tumor angiogenesis." (PMID 33614496, 2020).
tumor (continued). "From the perspective of tumor specificity, the apelin/Apj system might be a potential target for treatment and diagnosis." (PMID 32358530, 2020). "Thus, we re-inspected the U87MG xenografts and found that single invasive cells were detectable detaching from the compact GBM mass when APLN expression was knocked down in tumor cells (U87AKD)." (PMID 32545380, 2020). "Specifically, we found that tumor-derived, as well as ectopically infused, apelin-13 could rescue partially the vascular phenotype." (PMID 32545380, 2020). "Second, high circulating apelin could promote tumour growth but also increase tumour apelin expression directly, generating a positive feedback loop that drives TNBC progression." (PMID 32681609, 2020). "Thus, we also tested our experimental GBM models for vascular APLN expression and found that APLN expression was upregulated in newly forming tumor vessels (arrowheads) of the xenografts." (PMID 32545380, 2020). "Hence, the implication of the host circulating apelin on tumour progression remains largely unstudied." (PMID 32681609, 2020). "Apelin directly stimulates tumor cell proliferation, tumor cell migration and metastasis." (PMID 31690961, 2020). "On the basis of previous research and our current results, we speculate that CXCRs may interact with APLN/APLNR axis to regulate the immune state of the tumor microenvironment in ccRCC." (PMID 33324682, 2020). "In contrast, the C-terminally mutated peptide apelin-F13A (which had been used as an antagonist for physiological functions on APLNR before) was not able to rescue tumor angiogenesis." (PMID 32545380, 2020). "Knockdown of tumor cell-derived APLN massively reduced the tumor vasculature." (PMID 32545380, 2020). "Hence, we performed a tyrosine kinase activity assay (PamGene) on tumours samples to analyse the signalling pathways that were impacted by apelin." (PMID 32681609, 2020). "Interestingly, we did not observe brain metastases in the control group, indicating that apelin facilitated the seeding of circulating tumours cells into the brain." (PMID 32681609, 2020). "Finally, to assess the impact of apelin-controlled tumor angiogenesis on survival, we implanted the human GBM cells into APLNWT or APLNKO mice orthotopically." (PMID 32545380, 2020). "This suggests that apelin drives tumour growth mainly by acting on the tumour microenvironment." (PMID 32681609, 2020). "Interestingly, when APLN levels were decreased stepwise in the tumor microenvironment and the tumor cells, the cell behavior of the GBM cells changed towards increased invasiveness." (PMID 32545380, 2020). "Note that in situ hybridization for mouse APLN RNA shows that APLN is absent in tumor cells, as well as in the GBM microenvironment, of APLNKO mice, while APLN expression in APLNWT mice is specifically upregulated in endothelia of the tumor neo-vasculature (arrows)." (PMID 32545380, 2020). "Thus, vascular APLN expression seems to be essential for the formation of a mature tumor neo-vasculature that supports GBM growth." (PMID 32545380, 2020). "The effects of Apelin depletion on tumor cells and the cells of the tumor microenvironment might be model and context dependent." (PMID 31267692, 2019). "The apelin tumour/non-tumour ratio showed 2.5 times higher levels of apelin in tumour tissue." (PMID 31547096, 2019). "A decrease in apelin and its receptor could contribute to impaired cardiac function in the heart of tumor-bearing mice." (PMID 31851697, 2019). "Knockdown of APLN significantly suppressed tumor growth in nude mice (P < 0.05)." (PMID 31410213, 2019). "Little is known about the role of APLNR/APLN axis during oncogenesis/tumour growth." (PMID 30783205, 2019). "Although the Apelin/Apelin receptor pathway is downregulated in adulthood, it is frequently reactivated and upregulated in tumors, including in endothelial cells within the tumor microenvironment." (PMID 31267692, 2019).